FECH (ferrochelatase)
Diseases named in the same sentence as FECH in open-access papers (continued):
Sharing a sentence is not in itself a finding about the gene and the disease.
anemia (15 papers, 2010 to 2024). A reduction in the number of red blood cells, the amount of hemoglobin, and/or the volume of packed red blood cells. "It is not surprising that mutations in proteins responsible for ISC transfer can cause anemia because two of the eight enzymes catalyzing heme biosynthesis, namely aminolevulinate dehydratase and ferrochelatase, were identified to be iron–sulfur proteins." (PMID 38757931, 2024). "Our patient presented with anemia as lead causes inhibition of enzymes delta-aminolevulinic acid dehydratase and ferrochelatase causing inhibition of heme synthesis." (PMID 34178489, 2021). "Among the 11 predicted targets involved in the pathogenic process of anemia, FECH was shown relatively higher values of degree and closeness centrality, and was reported to be closely related to the production of heme." (PMID 30670967, 2018). "Anemias caused by defective heme synthesis, such as those due to deficiencies of erythroid-specific δ-aminolevulinate synthase or ferrochelatase, are characteristically microcytic and hypochromic." (PMID 21887333, 2011). "Additionally, iron deficiency anemia can be defined by an increase in the ZnPP/heme ratio, which is caused by the relative increase in zinc as a substrate for ferrochelatase when cells become iron-restricted." (PMID 36678152, 2023). "And based on the literature research, FECH was reported to be a mitochondrial membrane-associated protein catalyzing the terminal step of heme biosynthesis, of which the abnormal synthesis can lead to anemia." (PMID 30670967, 2018). "Farant and Wigfield reported that inhibition of ALAD, a cytosolic sulfydryl enzyme and ferrochelatase by lead resulted in depressed heme synthesis that ultimately led to anemia." (PMID 21042466, 2010). "The treatments of Rk3 and 20(S)-Rg3 of certain doses could reverse the decreased levels of heme and ferrochelatase, of which the abnormal synthesis can lead to anemia." (PMID 35873541, 2022). "Our studies reveal that CLPX mutations may cause anemia and porphyria via dysregulation of ALAS, FECH, and PPOX activities, as well as of iron metabolism." (PMID 34280433, 2021). "Anemia may develop with Pb poisoning via the inhibition of ferrochelatase and δ-aminolevulinic acid dehydratase (ALAD), the two of many enzymes involved in heme biosynthesis." (PMID 33927623, 2021). "While a zebrafish model of SCD does not exist currently, suppression of ATPase inhibitory factor 1 (atpif1α), a mitochondrial protein, produces profound anemia in zebrafish by interfering with heme synthesis through decreased catalytic efficiency of ferrochelatase." (PMID 26147622, 2015). "For example, Pb-induced anemia occurs via the inhibition of two enzymes of heme biosynthesis: ALAD and ferrochelatase." (PMID 33927623, 2021). "The inhibition of ferrochelatase and ALAD by lead decreases heme synthesis which leads to anemia." (PMID 33927623, 2021). "The function of FXN is not yet very clear in our eyes since the patients of FRDA have no systemic anemia, indicating that 2Fe–2S containing FECH is mildly, if some, affected." (PMID 37288145, 2021).
iron deficiency (12 papers, 2007 to 2025). "In case of iron deficiency, FECH uses its alternative substrate, zinc (Zn), to form zinc-protoporphyrin (ZnPP), which, however, cannot replace heme." (PMID 40017630, 2025). "Both reduced FECH expression/activity and iron deficiency would result in PPIX accumulation, but scientific evidence is missing that this plays a role in 5-ALA-induced PPIX accumulation in vivo." (PMID 36882505, 2023). "Often, reduced activity of the enzyme ferrochelatase (FECH) and iron deficiency are proposed to be linked to the PpIX accumulation in cancer cells." (PMID 38027504, 2023). "Due to the reduced activity of the rate-limiting enzyme ferrochelatase, as well as iron deficiency in the tumor tissue, in contrast to the normal one, there is an accumulation of an intermediate product of biosynthesis–protoporphyrin IX (PP IX)." (PMID 37721564, 2023). "In case of iron deficiency as observed in serum samples of severe COVID-19 patients, FECH was reported to catalyze the incorporation of other metals like zinc instead of iron into protoporphyrin IX, resulting in the formation of zinc protoporphyrin (ZnPP)." (PMID 35181867, 2022). "In EPP patients with deficient FECH, iron deficiency might lead to less PPIX accumulation by inhibiting ALAS2 but should also increase PPIX level by inhibiting FECH action." (PMID 34940556, 2021). "Moreover, iron deficiency and decreased ferrochelatase (FECH) activity may also contribute to PpIX accumulation." (PMID 41188567, 2025). "Therefore, the outcome on PPIX level might depend on the relative sensitivity of ALAS2 and FECH to iron deficiency." (PMID 34940556, 2021). "Reduced expression and activity of the enzyme ferrochelatase (FECH) and iron deficiency are commonly observed in cancer." (PMID 36882505, 2023). "In CEP, it could be hypothesized that without the induction of ALAS2 expression, such as seen in FECH deficient patient, iron deficiency efficiently succeeds in inhibiting ALAS2 mRNA translation via the IRE/IRP system." (PMID 34940556, 2021). "In iron deficiency, FKN was not capable of restoring FECH mRNA expression both at 24 h and 48 h of DFO treatments." (PMID 37373063, 2023).
porphyria (10 papers, 2016 to 2025). Porphyria is a group of diseases in which substances called porphyrins build up, negatively affecting the skin or nervous system. "The porphyrias are genetic disorders, each resulting from the deficiency of the FECH enzyme in the heme biosynthetic pathway." (PMID 33400006, 2021). "Human patients with porphyria display a similar phenotype because they carry mutations in ferrochelatase gene." (PMID 26967735, 2016). "INH induces ALAS1 protein expression while suppressing FECH, leading to the accumulation of ALA and PPIX and thereby increasing the risk of porphyria." (PMID 40559379, 2025). "At the Royal Prince Alfred Hospital in Australia, a cohort of 36 porphyria patients of European descent and their family members were evaluated for clinical history, biochemical profile and detection of pathogenic mutations in haem biosynthetic pathway genes (HMBS, CPOX, PPOX or FECH)." (PMID 27507172, 2016). "Xiao-Fei Kong and colleagues genotyped 52 Han Chinese volunteers without porphyria and reported that the AF of the FECH low-expression SNP locus c.315-48T>C was 41.35% among normal Han Chinese individuals." (PMID 39267094, 2024). "Similarly, while FECH is not a well-documented target for immune-mediated diseases, potential relevance may exist for certain red blood cell disorders or porphyrias, necessitating further investigation." (PMID 37845713, 2023).
bladder cancer (6 papers, 2017 to 2024). "In various cancers, including bladder cancer, inactive FECH results in reduced heme production and downregulation of PpIX catabolism, thereby favoring PpIX accumulation." (PMID 39201369, 2024). "It has been reported that the expression of FECH protein played an important role in PpIX accumulation in human bladder cancer cells." (PMID 30959982, 2019). "In bladder cancer, ferrochelatase expression was downregulated, and the PpIX contents of tumor tissue increased after ALA administration." (PMID 28257041, 2017). "Although ALA-PDT has been investigated in RT-112 bladder cancer cells previously, we are not currently aware of their ferrochelatase activity, and so this would be an interesting avenue of future research." (PMID 34218351, 2022).
glioblastoma (6 papers, 2011 to 2024). The most malignant astrocytic tumor (WHO grade IV). "Glioblastoma exhibits reduced FECH expression compared to normal brain tissue, contributing to PpIX accumulation." (PMID 38516394, 2024). "Reduced FECH expression has been demonstrated in many tissues and tumors, including glioblastoma multiforme." (PMID 35055109, 2022). "The authors proved that glioblastoma has a prominent downregulation of FECH mRNA expression when compared with normal brain." (PMID 35055109, 2022). "In some tumors, including glioblastomas, this PpIX buildup is augmented by partial downregulation of ferrochelatase (FECH), the enzyme that inserts ferrous iron into PpIX to give heme." (PMID 33564720, 2020). "This study has demonstrated significant downregulation of FECH mRNA expression in glioblastomas compared with normal brain tissues." (PMID 21304523, 2011). "Cells expressing FECH in normal brain and glioblastoma specimens were identified using immunohistochemistry." (PMID 21304523, 2011). "The density of FECH-positive cells was significantly lower in glioblastoma specimens compared with normal brain specimens under random fields of microscopic observation at the same magnification." (PMID 21304523, 2011). "Prominent downregulation of FECH mRNA expression was found in glioblastoma tissues compared with normal brain tissues, suggesting that FECH is responsible for PpIX accumulation in glioblastoma cells." (PMID 21304523, 2011). "In addition, the levels of FECH mRNA expression in glioblastoma were also found to be lower than those in normal brains." (PMID 30959982, 2019). "Ferrochelatase was predominantly immunolocalised in the majority of neurons and astrocytes in normal brain specimens, whereas faint staining was detected in neoplastic astrocytes in glioblastoma specimens." (PMID 21304523, 2011). "The expression levels of FECH mRNA were significantly lower in glioblastoma tissues (mean±s.e., 1.21±0.40; n=41) than that in normal brain tissues (5.71±2.36; P<0.05; n=15), diffuse astrocytoma tissues (3.89±0.92; P<0.05; n=17) and anaplastic astrocytoma tissues (4.60±0.75; P<0.005; n=8)." (PMID 21304523, 2011). "Since glioblastoma typically show strong fluorescence, we surprisingly observed significantly higher rather than lower FECH protein expression in the fluorescing group." (PMID 35665365, 2022).
Erythropoietic Porphyria (4 papers, 2011 to 2023). "Then, we will describe how iron availability can modulate the heme biosynthetic pathway activity, with a focus on ALAS2 and FECH regulation in patients with erythropoietic porphyrias." (PMID 34940556, 2021).
malaria (4 papers, 2013 to 2026). Malaria is a serious and sometimes fatal disease caused by a parasite that commonly infects a certain type of mosquito which feeds on humans. "To study the role of the dual heme sources in malaria parasite growth and development, we knocked out the first enzyme, δ-aminolevulinate synthase (ALAS), and the last enzyme, ferrochelatase (FC), in the heme-biosynthetic pathway of Plasmodium berghei (Pb)." (PMID 23935500, 2013). "While, ferrochelatase as a crucial enzyme in the heme synthesis pathway, has been knocked out in both rodent and human malaria models, with no significant changes observed in the growth of the ferrochelatase knockout strain compared to the wild-type strain." (PMID 41476774, 2026).
colon cancer (3 papers, 2011 to 2024). "In a colon cancer model with Caco-2 cells, loss of FECH was found to be protective against colon cancer tumorigenesis in vitro." (PMID 39201369, 2024). "Relevant studies have shown that changes in FECH expression were detected in human colon cancers and that loss of FECH has a tumor-suppressive effect on colon carcinogenesis in vitro, which was a potential tumor-suppressor gene for colon cancer." (PMID 36059798, 2022). "Researchers have found a correlation between the presence of attenuated FECH expression or molecular defects in FECH expression in cancerous tumors, which include urothelial and colon cancers, and the buildup of PpIX inside of the cells." (PMID 36059798, 2022). "Studies have shown that low expression or molecular defects of FECH in malignant tumours, such as colon cancer and urothelial cancer, is correlated with intracellular PpIX accumulation." (PMID 21304523, 2011).
leukemia (3 papers, 2021 to 2025). A malignant (clonal) hematologic disorder, involving hematopoietic stem cells and characterized by the presence of primitive or atypical myeloid or lymphoid cells in the bone marrow and the blood. "Increased PPIX formation and death was also observed in a T-lymphoblastoid ferrochelatase-deficient leukemia cell line, suggesting that PPIX elevation might serve as a potential strategy for killing certain leukemias." (PMID 37355765, 2023). "Our published TMT-labelled proteomics of primary leukemia samples compared to normal peripheral blood cells showed that the leukemic cells had increased iron-related proteins (FTH, FTL, TFRC, FECH, and TOM20)." (PMID 41188278, 2025).
liver disease (3 papers, 2009 to 2025). "Patients who have FECH mutations on both alleles or a gain of function mutation of ALAS2 have an increased risk of liver disease though together they account for only a small proportion of those with liver disease." (PMID 19744342, 2009). "Together these studies suggest that missense mutations that preserve significant amounts of residual activity may carry a lower risk of liver disease than 'null' mutations, a group that includes those misssense mutations that abolish FECH activity." (PMID 19744342, 2009). "Clinical findings of liver disease in the course of EPP were reported in approximately 5%–20% of patients and were associated with loss-of-function FECH variants." (PMID 40007872, 2025). "However, 'null' mutations associated with liver disease are found more frequently in patients without liver disease; an observation that indicates the probable importance of genetic factors outside the FECH locus and acquired factors in the pathogenesis of protoporphyric liver disease." (PMID 19744342, 2009).
malignant glioma (3 papers, 2016 to 2023). A grade III or grade IV glioma arising from the central nervous system. "Moreover, it is evident that the mechanism underlying PpIX accumulation in malignant glioma tissues involves an abnormality in porphyrin-heme metabolism, specifically decreased ferrochelatase enzyme activity." (PMID 27429612, 2016). "Correspondingly, a downregulation of FECH is considered to induce PpIX accumulation and tumor fluorescence in malignant gliomas." (PMID 36612300, 2023). "In the malignant glioma cells, the ferrochelatase activity was lower than in normal brain tissue." (PMID 28257041, 2017).
meningioma (3 papers, 2019 to 2025). A generally slow growing tumor attached to the dura mater. "Alternatively, differences in ferrochelatase activity in meningioma cell lines that can reduce the accumulation of PpIX may have been responsible for the lack of fluorescence visualization." (PMID 30594965, 2019). "Protein expression of ABCB6, ABCG2, FECH and CPOX was found in meningioma tissue and was correlated with fluorescence (p < 0.05, each), whereas this was not confirmed for mRNA expression." (PMID 36612300, 2023). "ABCB6, ABCG2, FECH and CPOX are expressed in meningioma tissue and are related to fluorescence." (PMID 36612300, 2023). "In samples from the bulk tumor, the median expression scores for ABCB6, ABCG2, FECH and CPOX were 9 (range: 2–12), 8 (range: 3–12), 9 (range: 1–12) and 9 (range: 1–12), respectively, and expression was similar comparing grade 1 and 2/3 meningiomas (p > 0.05 for each)." (PMID 36612300, 2023). "However, another report has indicated that tumor fluorescence intensity may be associated with the expression of key enzymes in the heme biosynthesis pathway, such as ferrochelatase, as well as transmembrane transporters involved in 5-ALA uptake within meningiomas." (PMID 40227799, 2025).
microcytic anemia (3 papers, 2021 to 2024). Anemia in which the red blood cell volume is decreased. "In addition, Pb inhibits ferrochelatase, the terminal enzyme in the heme biosynthetic pathway, and causes microcytic anemia." (PMID 35010453, 2021). "Microcytic anemia, seen in lead poisoning, is due to the inhibition of porphobilinogen synthase and ferrochelatase, which prevents porphobilinogen formation and the incorporation of iron into protoporphyrin IX leading to ineffective heme synthesis." (PMID 39258054, 2024).
prostate carcinoma (3 papers, 2019 to 2024). A carcinoma that arises from epithelial cells of the prostate gland. "The FECH/CROT signature can predict biochemical recurrence of prostate cancer patients in the MSKCC dataset and GSE70769." (PMID 31295943, 2019). "Therefore, as a component in the same pathway, FECH may also play important roles in androgen regulation in prostate cancer." (PMID 31295943, 2019). "In an in vitro model using prostate cancer cells (PC-3) treated with 5-aminolevulinic acid (ALA) and PDT, the efficiency was enhanced by using an FECH inhibitor." (PMID 39201369, 2024). "FECH does not significantly differentially expressed in primary prostate cancer compared with normal prostate." (PMID 31295943, 2019).
acute porphyrias (2 papers, 2025). "The diagnosis of hepatic porphyria was established through a combination of imaging studies, laboratory investigations, liver biopsy, and genetic testing, which revealed a pathogenic c.587G>T (p.C196F) mutation in the FECH gene." (PMID 41624744, 2025).
cholelithiasis (2 papers, 2018 to 2025). The presence of crystallized deposits forming in the gallbladder or biliary tree, primarily composed of cholesterol, bilirubin, and bile. "Liver involvement is observed in 5%–20% of patients harbouring loss-of-function FECH variants and its manifestations are heterogeneous, ranging from mildly elevated liver transaminases, cholelithiasis to severe acute cholestatic hepatitis/liver failure." (PMID 40007872, 2025).
Cholestatic liver disease (2 papers, 2025). "Interestingly, in the case presented here, two missense FECH mutations were found in a compound heterozygosity while the patient presented with progressive hepatocellular and cholestatic liver disease." (PMID 40007872, 2025).
colorectal cancer (2 papers, 2016 to 2021). A primary or metastatic malignant neoplasm that affects the colon or rectum. "In fact, ferrochelatase downregulation and loss of enzymatic activity correlates with an enhanced PpIX-dependent fluorescence in gastric and colorectal cancer cell lines." (PMID 27564260, 2016). "PpIX is complexed with Fe2+ to produce heme under the catalysis of ferrochelatase (FECH), and heme was reported to be related to the malignant process of colorectal cancer." (PMID 34553073, 2021). "Knockdown of IGHG1 reduced the expression and the activity of FECH protein, an enzyme involved in heme biosynthesis, in HT29 cells, which indicated that IGHG1 contributed to FECH activation in colorectal cancer." (PMID 34553073, 2021).
COVID-19 (2 papers, 2022 to 2023). A disease caused by infection with severe acute respiratory syndrome coronavirus 2. "The significantly lower level of N-methyl protoporphyrin in COVID-19 patients further supports these results, as it is known as a potent inhibitor of FECH." (PMID 35181867, 2022). "In addition, the inhibitor of ferrochelatase, N-methyl-protoporphyrin, was strongly decreased in COVID-19 patients and less so in convalescents." (PMID 35181867, 2022).
heart failure (2 papers, 2011 to 2022). Inability of the heart to pump blood at an adequate rate to meet tissue metabolic requirements. "UBN1, NGF and FECH genes displayed similar statistically significant regulation (up or down regulated) in hearts samples from heart failure patients but expression of the three remaining genes (TMEM79, FBXW7 and SLC43A2) could not be quantified, probably because of their low expression in heart." (PMID 21731613, 2011). "Analysis of the leucocyte transcriptome in 294 patients without overt heart failure revealed that levels of FECH, TMEM79, FBXW7, NGFB, ALK, UBN1, and SLC43A2 in peripheral blood were able to predict ALVD with 87% accuracy and 100% precision." (PMID 35722087, 2022).